IGLL1 (immunoglobulin lambda like polypeptide 1)
Description:
Critical for B-cell development.
Synonyms: CD179b; IGL1; IGVPB; IGL5; 14.1; AGM2; IGLJ14.1; IGLL; IGO; VPREB2
Tractability: Antibody: UniProt places it where antibodies can reach, with high confidence; its Gene Ontology location is reachable by antibodies, with high confidence; UniProt predicts a signal peptide or a membrane-spanning region. PROTAC: ubiquitination databases record sites on it.
Gene: Protein-coding gene on chromosome 22 (23,573,125 to 23,580,302, reverse strand). Ensembl gene ENSG00000128322.
Subcellular location: Endoplasmic reticulum; Secreted
Subcellular location (Human Protein Atlas): Endoplasmic reticulum; Predicted to be secreted
Pathways (Reactome):
Hemostasis: Cell surface interactions at the vascular wall
Gene Ontology:
Molecular function: protein binding; antigen binding
Biological process: immune response; immunoglobulin mediated immune response
Cellular component: extracellular region; endoplasmic reticulum; IgG immunoglobulin complex; membrane
Genetic constraint (gnomAD): Loss-of-function variants: 9 observed, 7.54 expected, observed/expected ratio (o/e) 1.19, 90% interval 0.71 to 1.84. That is too few expected variants to judge how well the gene tolerates losing a copy. Missense variants: 284 observed, 251.62 expected, observed/expected ratio (o/e) 1.13, 90% interval 1.02 to 1.25. Synonymous variants: 141 observed, 111.32 expected, observed/expected ratio (o/e) 1.27, 90% interval 1.1 to 1.46.
Gene-disease validity (ClinGen):
ClinGen rates the evidence that IGLL1 causes each of these diseases.
agammaglobulinemia 2, autosomal recessive (autosomal recessive): Moderate.
Homologues: Orthologues: macaque IGLL1 (91% identical), rabbit IGLL1 (57% identical), rat Iglc1 (37% identical), mouse Iglc1 (35% identical), mouse Iglc4 (32% identical), mouse Iglc3 (31% identical), mouse Iglc2 (31% identical). Paralogues in human: IGLL5 (62% identical), IGLC2 (42% identical), IGLC1 (41% identical), IGLC3 (41% identical), IGLC7 (41% identical), IGHG1 (23% identical), IGHG3 (23% identical), IGHG2 (23% identical), IGHM (23% identical), IGHG4 (23% identical), IGHA2 (22% identical), IGHA1 (21% identical), and 65 more.
Diseases named in the same sentence as IGLL1 in open-access papers:
IGLL1 is named in the same sentence as 27 diseases in open-access papers, as found by Europe PMC text mining. Sharing a sentence is not in itself a finding about the gene and the disease. The quoted sentences say what the papers report.
agammaglobulinemia (7 papers, 2018 to 2025). A decreased level of serum immunoglobulins. "A recently published study reported 17 cases of agammaglobulinemia caused by IGLL1 variants, the vast majority of which were identified through NBS." (PMID 40443574, 2025). "Before the implementation of newborn screening (NBS), only a few cases of agammaglobulinemia associated with IGLL1 variants had been reported." (PMID 40443574, 2025). "A recently published study reported 17 cases of agammaglobulinemia caused by IGLL1 variants, 13 of which were diagnosed through NBS." (PMID 40443574, 2025). "This study significantly expanded the known clinical phenotypes associated with IGLL1-related agammaglobulinemia." (PMID 40443574, 2025). "Additionally, four children with absent KRECs and normal TREC levels were found to carry variants in the IGLL1 gene that is associated with autosomal recessive IGLL1 agammaglobulinemia." (PMID 41459527, 2025). "Agammaglobulinemia with other inherited pattern were also concluded: AR agammaglobulinemia was associated with mutations in several other genes such as IGHM, IGLL1, CD79A, CD79B, BLNK, PIK3R1, and TCF3 genes; AD-related agammaglobulinemia was also found with LRRC8A and TCF3 gene mutations." (PMID 36140582, 2022). "In view of this patient’s clinical presentation and agammaglobulinemia, the differential diagnosis includes autosomal recessive forms of the disease (such as defects in IGHM, IGLL1, CD79A/B, PIK3R1, PIK3CD), as well as, more rarely, XLA." (PMID 41327272, 2025).
primary immunodeficiency (4 papers, 2016 to 2025). "An equally high overrepresentation (OVF = 20.83, q-value = 2.38 × 10−6) was determined for the “magenta” module that was enriched in genes that control primary immunodeficiency, including ADA, CD19, CD79A, IGLL1, TAP1, TAP2, TNFRSF13C, and ZAP70." (PMID 32873298, 2020).
B-cell lymphopenia (2 papers, 2025). "Here, we report two cases of B-cell lymphopenia along with IGLL1 variants identified through NBS in Ukraine." (PMID 40443574, 2025). "It enabled the early detection of three cases of XLA and four cases of B-cell lymphopenia associated with IGLL1 variants." (PMID 41459527, 2025). "The use of the KREC assay enabled the first-time identification in Ukraine of B-cell lymphopenias associated with variants in IGLL1 gene." (PMID 41459527, 2025). "The program identified previously unrecognized IEIs, such as IGLL1-associated B-cell lymphopenias, contributing to the enrichment of national genetic knowledge and patient registries." (PMID 41459527, 2025). "In the cases we presented, B-cell lymphopenia, along with IGLL1 variants, was identified through NBS." (PMID 40443574, 2025). "Both cases of B-cell lymphopenia associated with IGLL1 variants were detected in the western regions of Ukraine (Lviv and Ternopil)." (PMID 40443574, 2025). "A comprehensive analysis of all reported literature cases to date identified 25 patients with B-cell lymphopenia and IGLL1 variants." (PMID 40443574, 2025). "Thus, this study highlights the potential underdiagnosis of B-cell lymphopenia secondary to IGLL1 variants." (PMID 40443574, 2025). "Thus, the cases presented here expand the data on immunological changes and genetic variants associated with B-cell lymphopenia linked to IGLL1 variants, identified through NBS." (PMID 40443574, 2025). "Additionally, the use of KREC assay expanded the diagnostic capacity to include previously unrecognized B-cell disorders, such as IGLL1-associated B-cell lymphopenia." (PMID 41459527, 2025). "This study highlights the potential underdiagnosis of B-cell lymphopenia caused by IGLL1 variants." (PMID 40443574, 2025).
lymphoma (2 papers, 2022 to 2024). A malignant (clonal) proliferation of B- lymphocytes or T- lymphocytes which involves the lymph nodes, bone marrow and/or extranodal sites. "In comparison to lymphomas infected with ΔEBNA2 alone, the ΔEBNA2 + Myc tumors have much higher expression of IGLL1 (CD179B, surrogate light chain), DNTT (terminal deoxynucleotidyltransferase, TDT), RAG1 and IL7R." (PMID 38620028, 2024). "Of note, the P493-6 cell line expresses much lower levels of some BL-associated (and GC B cell expressed) cellular proteins in comparison to the N1, N3 and N4 stable cell lines derived from the ΔEBNA2 + Myc lymphomas, including CD10, GCSAM, BACH2, and CD179B (IGLL1)." (PMID 38620028, 2024).
atopic dermatitis (1 paper, 2025). "At the same time, none of the patients in whom the identified IGLL1 variant was detected during the examination of siblings or parents exhibited any symptoms except for one case of moderate atopic dermatitis at the age of 14 years." (PMID 40443574, 2025).
B cell deficiency (1 paper, 2025). A broad classification of disorders where circulating numbers of B lymphocytes are decreased or ineffective. "Based on cases identified by NBS, the incidence of B-cell deficiency due to IGLL1 variants in Austria, Czechia, and Switzerland was estimated to be at least 1.3 per 100,000 births." (PMID 40443574, 2025).
breast carcinoma (1 paper, 2024). "The results showed that IGLL1, SLAMF7, SLAMF1, CD48, and LRRC8A were closely associated with immune infiltration in breast cancer (p < 0.05)." (PMID 38388382, 2024). "On the other hand, CD48, SLAMF1, and SLAMF7 were highly expressed in HER2 + and triple-negative breast cancer (TNBC), and IGLL1 was highly expressed in ER + and TNBC tissues; These six key genes are closely associated with immune infiltration in breast cancer." (PMID 38388382, 2024). "In three different types of breast cancer cells, differential expression was also observed in genes including HERV-K_1q23.3, CD48, SLAMF1, SLAMF7, HERV-K_22q11.23, IGLL1, HERV-K_9q34.11, and LRRC8A." (PMID 38388382, 2024). "A total of 88 candidate genes related to breast cancer prognosis were screened, of which CD48, SLAMF7, SLAMF1, IGLL1, IGHA1, and LRRC8A were key genes." (PMID 38388382, 2024). "In breast cancer, the high expression of SLAMF1, SLAMF7, CD48, and IGLL1 is positively correlated with the infiltration of B cells, CD8 + T cells, CD4 + T cells, macrophages, neutrophils, and dendritic cells." (PMID 38388382, 2024). "We evaluated the correlation between the expression of IGLL1, SLAMF7, SLAMF1, CD48, and LRRC8A and the immune infiltration profile in breast cancer using data downloaded from TCGA." (PMID 38388382, 2024). "Comparing the gene expression between normal breast epithelial cells and four types of breast cancer cells, it was found that all four different types of breast cancer cells exhibited differential expression of theHERV-K_1q23.3, SLAMF1, HERV-K_22q11.23, IGLL1, HERV-K_9q34.11 and LRRC8A." (PMID 38388382, 2024). "Further research is needed to investigate these results, and the results of the drug sensitivity analysis indicated that IGLL1, SLAMF7, SLAMF1, CD48, and LRRC8A might decrease sensitivity to specific chemotherapy drugs, further affecting the treatment efficacy for breast cancer." (PMID 38388382, 2024).
chronic lymphocytic leukemia (1 paper, 2024). "In cancers like Hodgkin's lymphoma and chronic lymphocytic leukemia, IGLL1 also plays a crucial role in regulating the tumor microenvironment and determining the fate of malignant cells." (PMID 38388382, 2024).
X-linked agammaglobulinemia (1 paper, 2020). X-linked agammaglobulinemia (XLA) is a clinically variable form of isolated agammaglobulinemia, an inherited immunodeficiency disorder (see this term), and is characterized in affected males by recurrent bacterial infections during infancy. "Fourth, genetic mutations of non-X linked agammaglobulinemia encoding for pre-BCR and/or BCR complex (such as IGHM, CD79a, CD79b, and IGLL1 genes) and for activating mTOR signaling (such as PI3KD and PIK3R1 genes)." (PMID 33013854, 2020).
cancer (3 papers, 2020 to 2024). A tumor composed of atypical neoplastic, often pleomorphic cells that invade other tissues. "Upregulation of MS4A1, IGLL1, RAG1, and SEMA3A resulted in significantly decreased survival in pediatric cancer patients." (PMID 36497424, 2022). "Genes related to B and T cell maturation (e.g. CD37, CD79B, JCHAIN, IGLL1, VPREB3, CD52), ribosomal protein genes (RPS-*, RPL-*) and cancer/stress genes (e.g. PRAME, ARHGDIB, FOS, JUN) were within the most significantly deregulated genes between clusters in those samples." (PMID 32415257, 2020).
immunity disorders (1 paper, 2012). "The up-regulations of CCR4 and IGLL1 serve as indicators of immunity disorders in KBD patients." (PMID 22235245, 2012).
IGLL1 also shares sentences with these, for which no sentence is quoted: tumor (4 papers); acute lymphoblastic leukemia (1); amyloidosis (1); bladder cancer (1); diabetes (1); Ewing sarcoma (1); Hodgkins lymphoma (1); infection (1); influenza (1); melanoma (1); myeloid tumors (1); Nijmegen breakage syndrome (1); pediatric tumors (1); periodontitis (1); precursor T-cell lymphoblastic lymphoma (1); triple-negative breast carcinoma (1).